CISD3 (CDGSH iron sulfur domain 3)
Description:
Can transfer its iron-sulfur clusters to the apoferrodoxins FDX1 and FDX2. Contributes to mitochondrial iron homeostasis and in maintaining normal levels of free iron and reactive oxygen species, and thereby contributes to normal mitochondrial function.
Synonyms: Miner2; MiNT
Tractability: Small molecule: a structure with a bound ligand is known. PROTAC: its protein half-life has been measured.
Gene: Protein-coding gene on chromosome 17 (38,730,318 to 38,735,605, forward strand). Ensembl gene ENSG00000277972.
Subcellular location: Mitochondrion
Gene Ontology:
Molecular function: 2 iron, 2 sulfur cluster binding; metal ion binding
Biological process: protein maturation
Cellular component: mitochondrion; cytoplasm
Genetic constraint (gnomAD): Loss-of-function variants: 9 observed, 13.88 expected, observed/expected ratio (o/e) 0.65, 90% interval 0.39 to 1.13. The upper end of that interval is the gene's LOEUF score, 1.13, which puts it in group 4 of 6, group 1 being the genes least tolerant of losing a copy. Missense variants: 147 observed, 170.76 expected, observed/expected ratio (o/e) 0.86, 90% interval 0.75 to 0.99. Synonymous variants: 52 observed, 67.7 expected, observed/expected ratio (o/e) 0.77, 90% interval 0.61 to 0.97.
Homologues: Orthologues: chimpanzee CISD3 (98% identical), pig CISD3 (87% identical), dog CISD3 (83% identical), rabbit CISD3 (81% identical), guinea pig CISD3 (78% identical), mouse Cisd3 (76% identical), rat Cisd3 (41% identical), Drosophila melanogaster CG3420 (33% identical), Caenorhabditis elegans cisd-3.2 (28% identical). Paralogues in human: CISD2 (24% identical), CISD1 (19% identical).
Diseases named in the same sentence as CISD3 in open-access papers:
CISD3 is named in the same sentence as 8 diseases in open-access papers, as found by Europe PMC text mining. Sharing a sentence is not in itself a finding about the gene and the disease. The quoted sentences say what the papers report.
colorectal cancer (1 paper, 2024). A primary or metastatic malignant neoplasm that affects the colon or rectum. "In our research, the treatment of colorectal cancer cells with OMe-Ph-Elemene led to the modulation of several crucial proteins associated with oxidative stress and cell apoptosis, including TRIAP1, HMOX1, and CISD3." (PMID 39765827, 2024).
deafness (1 paper, 2024). An inherited or acquired condition characterized by the complete loss of the ability to hear from one or both ears. "CISD3 may play a role in regulating electron transport and oxidative phosphorylation, and diseases associated with this gene include Wolfram Syndrome, a disorder which is associated with childhood diabetes, optic atrophy and deafness (OMIM number 222,300)." (PMID 38969939, 2024).
iron deficiency (1 paper, 2024). "We have investigated the biochemical features of CISD3 at the atomic and in cellulo levels upon challenge with different stress conditions i.e., iron deficiency, exposure to hydrogen peroxide, and nitric oxide." (PMID 38354784, 2024).
melanoma (1 paper, 2025). A malignant, usually aggressive tumor composed of atypical, neoplastic melanocytes. "Analysis of the TCGA-SKCM and GTEx datasets revealed elevated expression of NF2, SUZ39H1, CDC25A, GLRX5, and CISD3 in melanoma tissues, in contrast with the reduced expression of VDR, PPARD, CAMKK2, NT5DC2, and CHP1A." (PMID 40860143, 2025). "AGO2-RIP-qRT‒PCR assays demonstrated that the NF2 and CISD3 mRNAs were markedly enriched in the AGO2-miR-150-3p complex, a finding corroborated by their upregulation in miR-150-3p knockout melanoma cells." (PMID 40860143, 2025).
cancer (3 papers, 2021 to 2024). A tumor composed of atypical neoplastic, often pleomorphic cells that invade other tissues. "Pan-cancer analysis from TCGA reveals that expression of CISD3 is generally elevated in various human cancers which are consequently associated with a higher hazard ratio and poorer overall survival." (PMID 34497268, 2021). "Of note, we present the first study to uncover the role of CISD3 in molecular biological characteristics of cancer and present a potential target predisposing cancer cells to an increased risk of ferroptotic cell death." (PMID 34497268, 2021). "Of note, this study firstly uncovered the role of CISD3 in molecular biological characteristics of cancer, and provided a potential target predisposing cancer cells to an increased risk of ferroptotic cell death." (PMID 34497268, 2021). "We wonder whether CISD3 could be associated with the molecular biological characteristics of cancer and be a potential indicator of tumor prognosis." (PMID 34497268, 2021). "Thus, CISD3 could serve as a promising therapeutic target, predisposing cancer cells to an increased risk of ferroptotic cell death." (PMID 34497268, 2021). "Recent studies have shown that CISD3 depletion increases glutaminolysis and mitochondrial oxidative phosphorylation, rendering cancer cells or hepatocytes vulnerable to xCT inhibition." (PMID 37345031, 2023). "These research findings demonstrate that CISD1, CISD2, and CISD3 have the potential to modulate ferroptotic cell death in cancer cells through the regulation of their ISCs." (PMID 37345031, 2023). "In this work, through pan-cancer analysis from TCGA, we revealed that expression of CISD3 is generally high in various human cancers." (PMID 34497268, 2021). "Herein, we report a member of the NEET protein family, CISD3, exerts a regulatory role in cancer progression and ferroptosis both in vivo and in vitro." (PMID 34497268, 2021). "Collectively, these findings demonstrate that CISD3 plays a role in the molecular biological characteristics of cancer." (PMID 34497268, 2021). "CISD3 is highly expressed in various human cancers, and numerous studies have demonstrated that silencing CISD3 results in heightened mitochondrial instability and iron accumulation, significantly accelerating lipid peroxidation and promoting the elevation of mitochondrial ROS." (PMID 39765827, 2024). "Higher expression of CISD3 was found in most cancers, such as BRCA, DLBC, LIHC, PRAD, SKCM, and THYM, and CISD3 expression exhibited a high hazard ratio in the overall survival (OS) and disease-free survival (DFS) of multiple cancer types." (PMID 34497268, 2021). "Thus, we proposed that CISD3 may play a regulatory role in cancer progression and iron metabolism." (PMID 34497268, 2021).
tumor (2 papers, 2021 to 2022). "Recent evidence suggests that CISD3 is necessary for tumor cell proliferation by inhibiting cell death." (PMID 35493303, 2022). "Further, the results from H&E staining showed that the pathological structure of the xenografts was dramatically destroyed in CISD3 silenced tumor tissues under the treatment of erastin." (PMID 34497268, 2021).
CISD3 also shares sentences with these, for which no sentence is quoted: optic atrophy (1 paper); Wolfram syndrome (1).